LEP (leptin)
Diseases named in the same sentence as LEP in open-access papers (continued):
Sharing a sentence is not in itself a finding about the gene and the disease.
Hepatic steatosis (continued). "The obesity profile of db/db mice is very similar to that of ob/ob mice, and due to their own unstable expression of leptin levels, they develop more severe diabetes than ob/ob mice, but have less hepatic steatosis than ob/ob mice." (PMID 39339720, 2024). "A case–control study was designed to evaluate the impact of three of the most common adipokines (Nrg4, leptin, and adiponectin) on hepatic steatosis in the early recovery phase following sleeve gastrectomy (SG)." (PMID 38632600, 2024). "Leptin is a protein-like hormone secreted by adipose tissue, and the degree of hepatic steatosis is positively correlated to its expression level." (PMID 39081791, 2024). "When stratified by gender, similar trends persisted, with both males and females showing higher leptin levels in the presence of steatosis, supporting the role of adipose tissue in the pathogenesis of fatty liver disease." (PMID 38738048, 2024). "SO also decreased serum glucose, lipid, and leptin levels and attenuated adipocyte hypertrophy and hepatic steatosis." (PMID 37107257, 2023). "In this study, loganin treatment inhibited HFD- and OVX-induced weight gain and fat deposition reduced metabolic abnormalities, such as hepatic steatosis and adipocyte expansion, and increased the plasma levels of insulin and leptin." (PMID 36902181, 2023). "A downregulation of adipokines, including resistin and leptin, involved in the progression of hepatic steatosis was observed after the administration of CT-1 recombinant protein." (PMID 37048824, 2023). "Research has shown that inhibiting Th17 and cytotoxic T (Tc) among T-cell subsets in VAT, along with activating Treg, can reduce plasma ALT and leptin levels, alleviating hepatic steatosis, inflammation, and fibrosis, thereby improving NAFLD." (PMID 38187139, 2023). "Leptin resistance contributes to liver steatosis by increasing appetite, and, possibly, decreasing energy expenditure." (PMID 36978847, 2023). "Numerous studies have shown the importance of leptin in the pathogenesis and progression of hepatic steatosis." (PMID 36737598, 2023). "Leptin can suppress both hepatic glucose production and lipogenesis at earlier stages of hepatic steatosis, however prolonged hyperleptinemia promotes pro-inflammatory and profibrogenic cascades leading to development of advanced liver fibrosis." (PMID 37980369, 2023). "Leptin possesses anti-adipogenic properties and is inversely correlated with the severity of hepatic steatosis." (PMID 38187139, 2023). "H&E and PAS staining of LEPTIN−/− pig livers at 12–22 months of age revealed features of early stage fatty liver disease; whereas the hepatocytes demonstrated obvious balloon degeneration and vacuolated necrosis consistent with middle and late stages." (PMID 37705071, 2023). "(Keywords: adipogenesis, barrier function, berberine, alkaloids, fatty liver disease, gegen qinlian decoction, glucose-metabolism, glycolipid metabolism, leptin, nf-kappa-b, ppar-gamma, tnf-alpha)." (PMID 38045760, 2023). "Visceral fat accumulation and related TG content, hepatic steatosis and related TG content, as well as worsened plasma leptin levels were either partially or completely reversed by FO supplementation." (PMID 35565762, 2022). "Overweight individuals with hepatic steatosis displayed increased immunoreactivity for leptin, and lower intensity of immunoreaction against visfatin and chemerin in the liver compared to subjects without histopathological changes in the organ." (PMID 35549673, 2022). "Overweight males with hepatic steatosis showed the highest expression of leptin and chemerin but lowest expression of visfatin compared to overweight men with normal liver structure or to lean individuals." (PMID 35549673, 2022). "The strongest immunoreactivity for leptin was noted in the liver of overweight males with hepatic steatosis, compared to subjects with normal hepatic structure and those with a lower BMI." (PMID 35549673, 2022).
Hepatic steatosis (continued). "Low levels of leptin with high levels of adiponectin were protective against hepatic steatosis, whereas high levels of leptin and resistin acted to increase hepatic fibrosis." (PMID 36364915, 2022). "In this regard, it would be of interest to study the potential beneficial effect of leptin on the reversibility of hepatic steatosis in the BTBR strain." (PMID 35409324, 2022). "For NAFLD and fat mass, leptin administration attenuated hepatic steatosis and reduced hepatic TC and TG levels." (PMID 36046814, 2022). "Overweight subjects with hepatic steatosis displayed increased immunoreactivity for leptin and weaker immunoreaction against visfatin and chemerin in the liver, compared to individuals with normal organ structure." (PMID 35549673, 2022). "Leptin administration reduced hepatic steatosis in ob/ob mice by restoring adipose tissue and hepatic expression of aquaglyceroporins." (PMID 35409324, 2022). "Expression of leptin and chemerin was enhanced in the liver of overweight individuals, with the highest expression observed in subjects with hepatic steatosis." (PMID 35549673, 2022). "Leptin replacement therapy in lipodystrophic patients leads to an improvement in ectopic lipid disposition and in fatty liver disease." (PMID 35677722, 2022). "Both DIO and DR dams consuming HE diet had hepatic steatosis (P < 0.001) and exhibited reduced leptin sensitivity in the arcuate nucleus (P < 0.001)." (PMID 35222059, 2021). "Previously, we found that maternal fructose intake provoked hypertriglyceridemia, liver triglyceride accumulation, and a diminished leptin response in mothers, along with an impaired leptin signaling and hepatic steatosis in their fetuses." (PMID 34684668, 2021). "Treatment of DIO mice with withaferin A reduces body mass by 23%, fat mass by 35%, endoplasmic reticulum stress, hepatic steatosis, leptin level in the blood, and increases the potency of leptin and energy expenditure." (PMID 34084149, 2021). "The failure of elevated leptin levels to correct hepatic steatosis lies in the generation of a state of resistance to this hormone." (PMID 34209386, 2021). "Significant weight gain, hepatic steatosis, increased arterial wall thickness and a trend towards elevated leptin levels were observed in this study." (PMID 34095511, 2021). "We therefore analysed the expression of leptin, since leptin has been reported to augment both inflammatory and profibrogenic responses in the liver and plays a role in the pathogenesis of hepatic steatosis." (PMID 34354697, 2021). "The severity of hepatic steatosis correlates with leptin levels, especially in patients with high BMI." (PMID 34209386, 2021). "Clearly, more in-depth preclinical studies are needed on the extent to which RYGB improves fatty liver disease, including its impact on inflammation and fibrosis, and the potential role played by the leptin system." (PMID 34064308, 2021). "Leptin and adiponectin are mainly secreted from adipose tissue and play essential roles in developing and progressing fatty liver disease." (PMID 34593018, 2021). "Fructose is also involved in liver steatosis and liver disease progression by promoting lipid synthesis, leptin resistance and the generation of long-lasting endotoxins." (PMID 32508961, 2020). "CAP values were different over different grades of hepatic steatosis in ultrasound and was correlated negatively with serum adiponectin and positively with serum leptin and HOMA2-IR." (PMID 32728230, 2020). "In mice fed with a HF diet, dietary intake of genistein reduced hepatic steatosis and adiposity, which was related to the elevation of adiponectin and the reduction of leptin in adipose tissue." (PMID 33383845, 2020). "Both elafin delivery approaches also significantly increased circulating leptin levels and significantly reduced circulating IFNγ levels, food consumption, fat mass gain, fasting blood glucose levels, and liver steatosis of the HFD-treated male mice." (PMID 32733043, 2020).
Hepatic steatosis (continued). "RD-treated leptin-deficient ob/ob male mice and HCD-treated male mice developed liver steatosis 39,40." (PMID 32733043, 2020). "While the secretion of more than 500 adipokines has been attributed to WAT, adiponectin and leptin are at present the most characterized with regard to their relationship with fatty liver." (PMID 32314869, 2020). "Paralleling the data found for BMI, levels of leptin were higher and levels of adiponectin significantly lower in patients with moderate and high degrees of hepatic steatosis." (PMID 32151020, 2020). "A meta‐analysis on circulating levels of leptin in humans affected by fatty liver or NASH demonstrated increased levels of this hormone in the more severe form of the disease." (PMID 32314869, 2020). "This leptin action can be easily understood by the fact that its administration to ob/ob and lipodystrophic mice prevents hepatic steatosis." (PMID 33316927, 2020). "Patients with hepatic steatosis diagnosed by TE had significantly higher serum levels of leptin (P < 0.001), insulin (P = 0.002), HOMA2-IR (P < 0.001) and lower levels of serum adiponectin (P = 0.015) compared to the patients without hepatic steatosis in TE." (PMID 32728230, 2020). "It has recently been shown that protection of hepatic steatosis by an ablation of adipocyte PLA2 is mediated by adipocyte hormone leptin." (PMID 32957701, 2020). "Bloodstream SIRT1, leptin and adiponectin (ELISA), total and trunk fat mass (FM) %, abdominal visceral adipose tissue, liver steatosis and epicardial fat thickness (EFT) were assessed." (PMID 33202604, 2020). "For example, in addition to all the general effects of leptin, this adipokine has been shown to better liver enzymes and hepatic fat content, thus attenuating different manifestations of fatty liver in patients with lipoatrophy and metabolic syndrome." (PMID 31178685, 2019). "This improved glycemic control was associated with decreased adiposity, improved adipokine profile (lower leptin, higher adiponectin), and alleviation of hepatic steatosis in aged mice." (PMID 30585393, 2019). "There are many CB1R antagonists, including inverse agonists and natural compounds that target CB1R and can reduce body weight, adiposity, and hepatic steatosis, and those that improve insulin sensitivity and reverse leptin resistance." (PMID 31035653, 2019). "In obese NAFLD patients, leptin levels correlate with the severity of fatty liver, thus suggesting the presence of leptin resistance, probably due to a failure in leptin signaling." (PMID 31178685, 2019). "In this regard, the relative abundance of Parabacteroides, a genus predominantly found in the gut of healthy individuals, negatively correlated with body weight gain, liver steatosis and damage, epididymal fat accumulation and leptin plasma levels." (PMID 30971408, 2019). "In this sense, a recent study has demonstrated the ability of brain leptin to protect from hepatic steatosis by decreasing de novo lipogenesis in rat liver." (PMID 31842467, 2019). "A low-carbohydrate ketogenic diet (LCKD) promotes the progression of hepatic steatosis in C57BL/6 wild-type mice, but improves the condition in leptin-deficient obese (ob/ob) mice." (PMID 31815184, 2019). "We have previously reported that melatonin can rescue liver steatosis in seven-day-old rats via leptin methylation and cellular apoptosis." (PMID 30424542, 2018). "We examined blood glucose, insulin, homeostasis model assessment of insulin resistance (HOMA-IR), Leptin, body weight, epididymal fat, hepatic steatosis, Aβ burden, glial activation, and nesting behavior in HFSTZ-APP/PS1 mice." (PMID 29258283, 2017). "Our results indicate that mSJH prevents hepatic steatosis by increasing leptin expression level and thereby activating lipid metabolism pathways." (PMID 28358008, 2017). "KBH-1 exhibits alleviating effects by improving hepatic steatosis and leptin resistance by up-regulating the activation of AMPK and suppressing the expression of PPARγ." (PMID 27618865, 2016).
Hepatic steatosis (continued). "The acute challenge of insulin or leptin also confirms lowered insulin and leptin sensitivity occurred during the development of hepatic steatosis upon HFHS dieting, further verifies the existence of impaired signaling transduction." (PMID 25658428, 2015). "Gain or loss of hepatic leptin action in mice has a profound impact on the phosphatidylinositol 3 kinase (PI3K) activity and hepatic steatosis (i.e. TG content)." (PMID 25658428, 2015). "As insulin sensitizers, metformin and rosiglitazone have been proved effective in the clinic to reduce the serum leptin levels and improve the situation of hepatic steatosis." (PMID 24838072, 2014). "As a result compound 7i was discovered to be a good leptin regulator and to improve hepatic steatosis symptoms in DIO mice." (PMID 24838072, 2014). "The observed leptin: adiponectin ratios and hepatic steatosis were also consistent with the establishment of an insulin-resistant state." (PMID 25013446, 2014). "The present study showed that the prenatal glucocorticoid induced programming liver steatosis at day 7 after delivery, possibly via altered leptin expression." (PMID 24822223, 2014). "These transcriptional regulators are of particular interest because of their involvement in hormonal and inflammatory signaling pathways, leptin regulation, glucose homeostasis, and hepatic steatosis." (PMID 24558408, 2014). "Although higher leptin levels are observed in clinical cases of feline hepatic lipidosis, they are likely to be related to increased adiposity." (PMID 24438337, 2014). "Similar effects of leptin on alleviating hepatic steatosis have also been illustrated in lipodystrophic patients." (PMID 23554788, 2013). "High consumption of dietary fructose is an important contributory factor in the development of hepatic steatosis in insulin or leptin resistance." (PMID 22991573, 2012). "In the current study, the strong positive correlation between leptin levels and hepatic steatosis area reinforces this pathophysiological mechanism, suggesting that leptin reduction may have directly contributed to lower hepatic lipid deposition." (PMID 40862455, 2025). "In contrast, no robust association was observed with hepatic steatosis, suggesting a potentially more specific role for leptin in hepatic fibrogenesis rather than intrahepatic lipid accumulation." (PMID 40507178, 2025). "↑FGF21 and leptin, ↓and adiponectin at baseline predicted new fatty liver." (PMID 40525016, 2025). "Butanoic acid impacts the i) increase of leptin release and insulin sensitivity, ii) decrease of hypercholesterolemia and hepatic steatosis, iii) decrease of HOMA-IR index and iv) modulation of cellular events that regulate the assembly and delivery of lipoproteins." (PMID 38904913, 2024). "In investigating the connection between insulin and leptin resistance in hepatic steatosis, Zhang and co-workers found that IR occurs initially, followed by the development of leptin resistance, and, subsequently, steatosis approximately two to three weeks later." (PMID 39286709, 2024). "However, the link between leptin and hepatic steatosis has generated differing conclusions, despite the frequent occurrence of leptin resistance in obese individuals." (PMID 39286709, 2024). "However, after treatment with leptin, ob/ob mice showed not only a reduction in abnormal indicators, but also a partial improvement in liver steatosis." (PMID 39339720, 2024). "Furthermore, the administration of SO in HFD-induced obese mice reduced body weight gain, improved hepatic steatosis, lowered serum glucose and lipids, and restored dysregulated adipokines (leptin and adiponectin)." (PMID 37107257, 2023). "In conclusion, leptin may seemingly protect against hepatic steatosis in the initial stages of the disease." (PMID 37753211, 2023).
Hepatic steatosis (continued). "Moreover, a recent report shows that the injection of leptin in rats fed a high-fat diet results in reduced hepatic steatosis due to the increased export of hepatic TAG to the plasma via VLDL." (PMID 37764693, 2023). "In contrast, significant reductions in blood lipid and leptin levels of about 30% were observed in mice given rcREG3A which is consistent with the results obtained in ob/ob mice, as well as a trend toward reduced hepatic steatosis." (PMID 36918710, 2023). "Compared with Leptin−/− rats, we discovered that the alteration of JAK2-STAT3 and AMPK signaling pathways mediates β-oxidation and mitochondrial autophagy respectively in LEPTIN−/− pigs, which in turn enhanced oxidative stress and promoted the development of fatty liver to fibrosis." (PMID 37705071, 2023). "Moreover, Leptin−/− pig developed fatty liver, non-alcoholic steatohepatitis and hepatic fibrosis with age." (PMID 37705071, 2023). "Furthermore, the leptin to adiponectin ratio and arterial stiffness were found to correlate with hepatic steatosis severity." (PMID 35042855, 2022). "Leptin resistance might facilitate the accumulating fat in the liver and explain the occurrence of hepatic steatosis." (PMID 35911124, 2022). "Expression of the leptin and chemerin genes was enhanced in the liver of overweight individuals compared to those with normal body weight, with the highest expression observed in overweight subject with hepatic steatosis." (PMID 35549673, 2022). "Leptin is a liporegulatory adipokine which can display a protective role on pancreatic beta cells and liver steatosis but also increase the risk of inflammation in non-HIV infected patients." (PMID 35355551, 2022). "We further speculate whether a state of postpartum leptin-resistance contributes to the consistent, and often severe, liver steatosis that was observed in dams fed HE diet." (PMID 35222059, 2021). "Chronic infusions of leptin to early lactating cows effectively reduced lipid levels in the liver by 28%, lending support to a hypothesis that restoring leptin signaling in HE-fed rat dams would also reduce hepatic steatosis." (PMID 35222059, 2021). "Indeed, ob/ob mice and fa/fa Zucker rats fail to develop fibrosis during hepatic steatosis or toxin administration, demonstrating that leptin plays a significant role in this process." (PMID 33935782, 2021). "Leptin function in hepatocytes protects from hepatic steatosis and protects from hepatic injury, whereas it activates HSCs with the production of α-smooth muscle actin, collagen, and TIMP-1, leading to hepatic fibrosis, and upregulates the expression of TGF-β1 in Kupffer cells." (PMID 33671547, 2021). "Leptin prevents liver steatosis in animal models by affecting both lipid and glucose metabolism." (PMID 33324348, 2020). "Among patients achieving SVR, at 24 weeks post-IFN-based therapy, sex and BMI were associated with leptin, adiponectin, and PAI-1 levels; hepatic steatosis and the aspartate aminotransferase-to-platelet ratio index with adiponectin levels; and the HOMA-IR score and HCV genotype with PAI-1 levels." (PMID 33167521, 2020). "The results suggest that elafin inhibits liver steatosis via leptin expression." (PMID 32733043, 2020). "Leptin may protect the liver from hepatic steatosis at the initial stage of the disease but also acts as an inflammatory and fibrogenic marker when the disease progresses." (PMID 33324348, 2020). "In conclusion, it seems that in the initial stages of the disease, leptin may protect against hepatic steatosis." (PMID 33324348, 2020). "In both NAFLD and psoriasis, higher serum levels of leptin were found, which seemed to promote development of fatty liver and mediate skin proliferative and anti-apoptotic processes in T-cells, increasing secretion of pro-inflammatory cytokines by keratinocytes." (PMID 31540048, 2019).